TNFRSF11B (TNF receptor superfamily member 11b)
Diseases named in the same sentence as TNFRSF11B in open-access papers (continued):
Sharing a sentence is not in itself a finding about the gene and the disease.
ovarian carcinoma (1 paper, 2021). A malignant neoplasm originating from the surface ovarian epithelium. "For example, TNFRSF11B exhibited a cancer-specific behaviour in ovarian cancer by contrast to breast, where it was found to be down-regulated and was proposed as a potential prognostic biomarker." (PMID 34062972, 2021).
ovarian granulosa cell tumor (1 paper, 2020). A granulosa-stromal cell tumor that arises from the ovary. "Microarray analysis in mouse ovarian granulosa cell tumors (GCT) revealed the ectopic expression of TNFRSF11B as a bone marker." (PMID 32455542, 2020).
periodontal disease (1 paper, 2024). "Mutations in the TNFRSF11B gene are linked to various conditions, including juvenile Paget’s disease, temporomandibular joint ankylosis, and alveolar bone loss associated with periodontal disease." (PMID 39765683, 2024).
pneumonia (1 paper, 2021). An acute, acute and chronic, or chronic inflammation focally or diffusely affecting the lung parenchyma, caused by an infection in one or both of the lungs (by bacteria, viruses, fungi, or mycoplasma.). "High TNFRSF11B expression typically had a later TNM stage (p = 0.067), a higher frequency of lymph node (p = 0.029) and lymphovascular (p = 0.007) invasion, and a higher incidence of pneumonia (p = 0.056) than their counterparts." (PMID 34938284, 2021). "Patients with high TNFRSF11B expression typically had a late TNM stage (p = 0.067), a high frequency of lymph node (p = 0.029) and lymphovascular invasion (p = 0.007), and a high incidence of pneumonia (p = 0.056)." (PMID 34938284, 2021).
postmenopausal osteoporosis (1 paper, 2022). Metabolic disorder associated with fractures of the femoral neck, vertebrae, and distal forearm. "Single nucleotide polymorphism in TNFRSF11B, which encodes OPG, is associated with postmenopausal osteoporosis." (PMID 35163028, 2022).
preeclampsia (1 paper, 2021). Preeclampsia is a hypertensive disorder of pregnancy that is characterized by new-onset hypertension with proteinuria presenting after 20 weeks of gestation, and depending on mild or severe forms may initially present with severe headache, visual disturbances, and hyperreflexia. "TNFRSF11B, also known as osteoprotegerin, is a secreted factor that is a key regulator in bone metabolism, but is also pro-angiogenic, and has been associated with preeclampsia and diabetes mellitus in human pregnancies." (PMID 34299281, 2021).
psoriasis (1 paper, 2013). An autoimmune condition characterized by red, well-delineated plaques with silvery scales that are usually on the extensor surfaces and scalp. "Other cytokines and receptors with low expression levels and consistently minimal or no changes in psoriasis (IL13, TNFRSF11A, TNFRSF11B, and TNFSF11) showed similar results across all three platforms." (PMID 23308107, 2013).
pulmonary arterial hypertension (1 paper, 2024). Pulmonary arterial hypertension (PAH) is a group of diseases characterized by mean pulmonary artery pressure >20 mmHg and elevated pulmonary arterial resistance leading to right heart failure. "A therapeutic antibody targeting TNFRSF11B attenuated pulmonary arterial hypertension by reducing the proliferation and migration of the pulmonary artery smooth muscle cells." (PMID 38333413, 2024).
rheumatic diseases (1 paper, 2017). "Previous studies have been evaluated in postmenopausal women without rheumatic diseases, observing a probable association between polymorphisms in the TNFRSF11B gene and OP in different populations, with nonconclusive results." (PMID 28758134, 2017).
Sepsis (1 paper, 2025). Sepsis is defined as life-threatening organ dysfunction caused by a dysregulated host response to infection. "Interestingly, increased TNFRSF11B has also been reported to be elevated in the plasma of patients with sepsis–acute respiratory disease syndrome (ARDS) associated with vascular endothelial dysfunction." (PMID 40687705, 2025).
thyroid tumor (1 paper, 2022). A benign or malignant neoplasm affecting the thyroid gland. "We also integrated differentially downregulated DEGs from the datasets and identified six downregulated DEGs, namely, MPPED2, TNFRSF11B, FHL1, CRABP1, MATN2, and TFF3, collectively known as thyroid tumor-downregulated genes (TTDGs)." (PMID 35990603, 2022).
ulcerative colitis (1 paper, 2016). An inflammatory bowel disease involving the mucosal surface of the large intestine and rectum. "We have concluded that low OPG levels may be associated with osteoporosis in ulcerative colitis, but it is not correlated with the c.-223C > T polymorphism in the TNFRSF11B gene." (PMID 27639566, 2016).
vitiligo (1 paper, 2024). Generalized well circumscribed patches of leukoderma that are generally distributed over symmetric body locations and is due to autoimmune destruction of melanocytes. "Notably, proteins such as IL-17C, CXCL10, NKR2B4 (CD244), and TNF receptor superfamily member 11b (TNFRSF11B) exhibited bidirectional causality with vitiligo." (PMID 38660673, 2024). "Interestingly, through MR analysis, we identified TNFRSF11B, TNF alpha induced protein 3 (TNFAIP3), TNF superfamily member 12 (TNFSF12) as potentially protective factors against vitiligo, which may explain why some patients experience depigmentation after using TNF inhibitors." (PMID 38660673, 2024).
tumor (33 papers, 2010 to 2026). "TNFRSF11B is crucial in immune responses and tumorigenesis, influencing the tumor microenvironment through the RANK-RANKL signaling pathway, which promotes tumor cell proliferation and metastasis." (PMID 40018411, 2025). "We found that genes with a hazard ratio >1 (STC2 and TNFRSF11B) were expressed at higher levels in tumor tissues compared to normal tissues, with a significant and meaningful increase." (PMID 39119088, 2024). "Tumor development was monitored every three days while anti- PD1/PD-L1 therapies were given every three days and HMOX1/MMP9/TNFRSF11B antibody treatments were given every day until tumor capture on the ninth day." (PMID 36189226, 2022). "In addition, six genes, KRT18, ARPC5L, ACTG1, ARPC2, EZR, and YWHAZ, were simultaneously enriched in tumors and tumor tissues highly expressing TNFRSF11B, which may enhance pathogenic E. coli focal adhesion, actin filament binding, and cadherin binding, as demonstrated by GO functional analysis." (PMID 34938284, 2021). "TNFRSF11B also presented stronger transcriptional activity in tumor tissues than in paired colon epithelium (p <0.001)." (PMID 34938284, 2021). "Knockdown of TNFRSF11B in MGC803 cells markedly reduced the tumor size (P=0.049) and weight of xenografts (P=0.014)." (PMID 32398963, 2020). "A number of studies have suggested that TNFRSF11B was also considered as a survival factor for tumor cells inhibiting tumor cell apoptosis." (PMID 32398963, 2020). "In vitro studies suggested that TNFRSF11B exerted tumor-promoting effects by binding to TRAIL 27-29, thereby preventing induction of apoptosis." (PMID 32398963, 2020). "Among the genes involved in the hepatic fibrosis pathway, expression of the IGFBPs, COL4A1, COL4A2, MMP9 and TNFRSF11B was restored in 143BNSC and 143BGBM tumours." (PMID 27551510, 2016). "Additionally, CSC markers ADM, DLGAP5, S100A9, and TNFRSF11B showed consistent overexpression at both RNA and protein levels in tumor samples, with significantly lower expression in normal tissues." (PMID 40243557, 2025). "Overexpression of TNFRSF11B can promote tumor growth and metastasis." (PMID 36834821, 2023). "Finally, we observe the changes in tumor volume, the expression of inflammation-related genes, and tumor immune cell infiltration in the tumor to explore the synergistic mechanism of HMOX1/MMP9/TNFRSF11B and PD1/PD-L1 in HCC." (PMID 36189226, 2022). "Consistent with previous studies, the expression of S100A9 in tumor cells was significantly increased after M2 macrophages were co-cultured, and the expression of TNFRSF11B was significantly reduced, which may increase the malignancy of tumor cells." (PMID 35397536, 2022). "Our data suggest that while TNFRSF11B can potentially exhibit diagnostic potential, even differentiating between primary and recurrent tumours, it does not have any predictive power for the overall patient outcome." (PMID 34062972, 2021). "These in vitro and in vivo results support the tumor progression role of TNFRSF11B in GC." (PMID 32398963, 2020). "In addition, TNFRSF11B also induces angiogenesis, one of the hallmarks of cancer, thus facilitating tumor growth." (PMID 32398963, 2020). "Among them, EGFR(7p11.2), TWIST1(7p21.2), RAC1(7p22), MTDH(8q22.1), CCNE2(8q22.1), TNFRSF11B(8q24) and GRB2(17q25) might be good candidates, as they are reportedly associated with invasiveness and metastasis of tumor cells." (PMID 23457519, 2013). "TNFRSF11B, a member of the TNF receptor superfamily, can inhibit tumor apoptosis by binding to a TNF-related apoptosis-inducing ligand." (PMID 36834821, 2023). "Interestingly, some of the common down-regulated genes, such as EPHA7 and NSUN7, are known for both their tumor suppressing and promoting roles, or are associated with overall survival (OS) (SLC22A31), while others have clear pro-tumorigenic roles (ADGRF1, LOX, LY6G5C, SNAI2, TNFRSF11B, ZNF233)." (PMID 36769365, 2023).
tumor (continued). "Specifically, four genes (RN7SK, TNFRSF11B, NDUFB5 and RARRES3) were shown to be progressively up-regulated in primary and recurrent tumours compared to normal." (PMID 34062972, 2021). "Several genes involved in the immune system were identified as deregulated in both studies, such as interleukins, chemokines, APLN, TNFRSF11B, TNFS9, TCF7, AZGP1, strengthening the role of tumour extracellular environment alterations in the CRC biology." (PMID 31949199, 2020). "CD3+CD4+ T cells from 4T1 tumors expressed minimal levels of Tnfrsf11b, further emphasizing the differential immune programming induced by metastatic versus nonmetastatic tumor microenvironments." (PMID 41364090, 2026). "The S2 subtype of mesenchymal tumor cells overexpressed MUC16 and TNFRSF11B, which might lead to immune resistance." (PMID 36553542, 2022). "A negative correlation was observed between TNFRSF11B expression levels and the infiltration of activated memory CD4+ T cells into the tumor microenvironment using this dataset." (PMID 34938284, 2021).
cancer (28 papers, 2013 to 2025). A tumor composed of atypical neoplastic, often pleomorphic cells that invade other tissues. "Several genes regulated by HCQ in Ca9-22 cells have been identified as potential cancer therapy targets, including TNFRSF11B, CASP6, BIRC2, and BIRC5." (PMID 41303490, 2025). "TNFRSF11B can protect cancer cells from apoptosis by sequestering TRAIL, thereby blocking TRAIL-induced extrinsic apoptotic signaling." (PMID 41303490, 2025). "Of these eight PRS genes, three (BMP5, TNFRSF11B, and IGFBP2) are immune-related genes, and their association with the prognosis of cancer patients has been previously reported." (PMID 35535221, 2022). "We demonstrated that CEACAM6 expression was significantly upregulated in cancer tissues that had high TNFRSF11B expression." (PMID 34938284, 2021). "TNFRSF11B overexpression has multiple implications in cancer invasion, metastasis, as well as poor prognosis." (PMID 33297339, 2020). "Our findings regarding TNFRSF11B rs2073618 GG seem to be new in the context of cancer survival." (PMID 36900216, 2023). "TNFRSF11B is a potential plasma biomarker for the clinical diagnosis of various cancers." (PMID 33643183, 2021). "This includes several potential cancer related genes like EDA2R (minimum p-value = 3.7×10−31), and multiple other members of the tumor necrosis factor receptor superfamily like TNFRSF11B (minimum p-value = 1.3×10−12) and TNFRSF8B (minimum p-value = 1.1×10−13)." (PMID 41404623, 2025). "In our study, we identified six signature genes, namely TNFRSF11B, METTL7B, SSTR2, OXTR, CDKN2C, and H19 which have been extensively studied in the past and are known to play a significant role in cancer." (PMID 37713112, 2024). "The findings indicated a prevalence of hypomethylation in ECM-SRGs among patients with various cancers (KIRC, COAD, LIHC, UCEC, THCA, BRCA, etc.), and hypermethylation of TNFRSF11B among patients with PRAD, ESCA, LUSC, HNSC, BRCA, and THCA (FDR ≤ 0.05)." (PMID 37985530, 2023). "TNFRSF11B and TNFSF11 were also incorporated into our analysis because of their importance in the regulation of bone metabolism and cancer cell invasiveness." (PMID 36011038, 2022). "TNFRSF11B stimulates the secretion of CXCL12, which was suggested to contribute to TC development by regulating cancer cell migration and invasion." (PMID 33240576, 2020). "Upregulated genes included members of the tumor necrosis factor superfamily (TNFRSF9, TNFRSF11B, and TNFSF8), ABC transporters (ABCB1 and ABCG2), and nuclear factor (NF)-κB-related genes (NFKB2 and RELB), all of which induce stemness in cancer cells." (PMID 28423353, 2017). "PIK3CA-mutant cancers displayed higher expression of 12 of the 17 Wnt genes compared to PIK3CA wild-type tumors, including five Wnt target genes (LEF1, MYCN, FZD7, SFRP2, and TNFRSF11B) and seven Wnt signaling components (TCF7L1, TCF7L2, CTNNB1, FZD4, SFRP1, WNT5A, and MSX2)." (PMID 34035258, 2021).
infection (6 papers, 2016 to 2025). The state of being infected such as from the introduction of a foreign agent such as serum, vaccine, antigenic substance or organism. "Comparing infected and uninfected cells, one of the most significantly differentially expressed genes at 3 hours after infection was the tumor necrosis factor receptor superfamily member 11B (TNFRSF11B)." (PMID 37615437, 2023). "The number of genes whose expression had increased during the period of infection with T. gondii was significantly higher than those whose expressions had decreased (18 versus 1) and Tnfrsf11b had the highest rate of gene expression." (PMID 32963738, 2020).
CNS tumors (1 paper, 2024). "Besides, TNF receptor superfamily member 11b (TNFRSF11B) shows weak positive causality with benign CNS tumors as well (Weighted median beta = 0.1243, p = 0.03215)." (PMID 39043735, 2024).
kidney disease (1 paper, 2024). "Furthermore, certain vitamin D DEGs associated with inflammation, such as TLR4 and TNFRSF11B, showed a significant upregulation with the progression of kidney disease." (PMID 38978780, 2024).
TNFRSF11B also shares sentences with these, for which no sentence is quoted: cardiovascular diseases (3 papers); chronic periodontitis (2); osteopetrosis (2); Abdominal obesity (1); adenoma (1); anemia (1); ankylosing spondylitis (1); breast tumors (1); Cachexia (1); calcification (1); cognition (1); colon adenocarcinoma (1); colorectal tumor (1); coronary artery disease (1); esophageal cancer (1); fractures (1); ghosal hematodiaphyseal dysplasia (1); glioblastoma (1); hematological disease (1); Hypercholesterolemia (1); hypothyroidism (1); juvenile Paget disease (1); leukaemia (1); lupus nephritis (1); metabolic dysfunction-associated steatohepatitis (1); metastatic melanoma (1); neutropenia (1); osteomyelitis (1); otosclerosis (1); Partington syndrome (1).
A further 6 diseases each share a sentence with TNFRSF11B in 1 paper.